LDB3 (LIM domain binding 3)
Description:
May function as an adapter in striated muscle to couple protein kinase C-mediated signaling via its LIM domains to the cytoskeleton.
Synonyms: KIAA0613; ZASP; PDLIM6; CMD1C; CMD2L; CMH24; CMPD3; CYPHER; LDB3Z1; LDB3Z4; LVNC3; MFM4; ORACLE
Tractability: Small molecule: a structure with a bound ligand is known. PROTAC: ubiquitination databases record sites on it.
Gene: Protein-coding gene on chromosome 10 (86,666,664 to 86,736,159, forward strand). Ensembl gene ENSG00000122367.
Subcellular location: Cytoplasm, perinuclear region; Cell projection, pseudopodium; Cytoplasm, cytoskeleton; Cytoplasm, myofibril, sarcomere, Z line
Subcellular location (Human Protein Atlas): Cytosol; Focal adhesion sites; Nucleoplasm
Gene Ontology:
Molecular function: cytoskeletal protein binding; protein binding; actin binding; muscle alpha-actinin binding; protein kinase C binding
Biological process: actin cytoskeleton organization; heart development; muscle structure development
Cellular component: cytoskeleton; Z disc; adherens junction; filamentous actin; stress fiber; perinuclear region of cytoplasm; pseudopodium
Genetic constraint (gnomAD): Loss-of-function variants: 49 observed, 71.93 expected, observed/expected ratio (o/e) 0.68, 90% interval 0.54 to 0.86. The upper end of that interval is the gene's LOEUF score, 0.86, which puts it in group 3 of 6, group 1 being the genes least tolerant of losing a copy. Missense variants: 928 observed, 1,006.7 expected, observed/expected ratio (o/e) 0.92, 90% interval 0.87 to 0.97. Synonymous variants: 387 observed, 409.85 expected, observed/expected ratio (o/e) 0.94, 90% interval 0.87 to 1.03.
Gene-disease validity (ClinGen):
ClinGen rates the evidence that LDB3 causes each of these diseases.
cardiomyopathy, dilated, 2l (autosomal recessive): Strong.
dilated cardiomyopathy 1C (autosomal dominant): Limited.
arrhythmogenic right ventricular cardiomyopathy (autosomal dominant): Disputed.
hypertrophic cardiomyopathy (autosomal dominant): Disputed. A condition in which the myocardium is hypertrophied without an obvious cause.
Homologues: Orthologues: chimpanzee LDB3 (91% identical), macaque LDB3 (90% identical), mouse Ldb3 (89% identical), rat Ldb3 (88% identical), rabbit LDB3 (86% identical), guinea pig LDB3 (84% identical), dog LDB3 (72% identical), tropical clawed frog ldb3 (60% identical), zebrafish ldb3b (21% identical). Paralogues in human: PDLIM5 (34% identical), PDLIM7 (30% identical), PDLIM1 (16% identical), PDLIM4 (14% identical), PDLIM3 (13% identical), PDLIM2 (11% identical), PRICKLE4 (11% identical).